FUT8 (fucosyltransferase 8)
Diseases named in the same sentence as FUT8 in open-access papers (continued):
Sharing a sentence is not in itself a finding about the gene and the disease.
tumor (continued). "Tumor sections obtained from the castrated animals that were stained with FUT8 antibody, demonstrated a significant higher expression of FUT8 compared to the tissue sections from uncastrated controls, suggesting the induction of FUT8 under androgen-restricted conditions." (PMID 32085441, 2020). "Limited xenograft tumor growth in vivo with Fut8 KO HepG2 is also observed." (PMID 32626713, 2020). "Studies are currently underway in our laboratory to retrospectively evaluate FUT8 expression in tumor tissue microarrays (TMAs) cohorts to interrogate our hypothesis." (PMID 32085441, 2020). "In each tumor type, FUT8 expression showed significant (p< 0.05) correlation with one or more clinicopathological parameters; these included patient gender, molecular subgroup, histological grade, TNM stage, estrogen receptor, progesterone receptor, and recurrence status." (PMID 33323540, 2020). "Similarly, other reports also showed that the FUT8 and FUT family were associated with the proliferation of tumor cells." (PMID 31022917, 2019). "The stage-wise importance and contributions of core fucosylation to tumorigenesis has been clearly illustrated in a mouse model of HCC development, where FUT8 activity is required for the development of well-vascularized tumors, whereas knockout of FUT8 completely abolishes tumor formation." (PMID 31450600, 2019). "However, none of the clinicopathological parameters, including age, gender, tumor location, histological differentiation, TNM staging, was associated with FUT8 protein expression in our cohort." (PMID 29975776, 2018). "Core fucosylation (addition of fucose in α-1,6-linkage to core N-acetylglucosamine of N-glycans) catalyzed by fucosyltransferase 8 (FUT8) is critical for signaling receptors involved in many physiological and pathological processes such as cell growth, adhesion, and tumor metastasis." (PMID 28982386, 2017). "The Fut8 in adjacent tissues was significantly higher than that in tumor tissues (P<0.05)." (PMID 24732908, 2014). "In animal models, inhibition of Fut8 activity by gene knockout, RNA interference, and small analogue inhibitors resulted in reduced tumor growth/metastasis, downregulation of the immune checkpoint molecules PD-1, PD-L1/2, and B7-H3, and reversal of the inhibited state of the tumor microenvironment." (PMID 40373023, 2025). "In addition, applying the FUT8 knockout mammalian cell lines to antibody production can obtain antitumour monoclonal antibodies with better performance, defucosylated IGg1 antibodies have been applied in tumour therapy." (PMID 34093814, 2021). "Together these findings suggest that FUT8 can damper tumour-infiltrating immune cells, and that targeting core fucosylation may inhibit tumour growth, thus reducing PD-1/PD-L1 interactions and weakening tumour immune evasion." (PMID 33466384, 2021). "However, it should be noted that the inhibition of FUT8 may considerably impact normal human cells, thus limiting the application of FUT8 inhibitors in tumor therapy." (PMID 33531990, 2021). "However, it should be noted that the inhibition of FUT8 may considerably impact normal human cells, thus limiting the application of FUT8 inhibitors in tumour therapy 149,151." (PMID 34093814, 2021). "FUT8 may serve as a therapeutic target to reverse chemotherapy resistance in tumor cells." (PMID 31022917, 2019). "In addition, it has been reported that α-1, 6-fucosyltransferase (Fut8) activity and expression is increased in several human cancers, suggesting a role for this enzyme in tumor development and progression, such as HCC, colorectal cancer, nonsmall cell lung cancer and ovarian serous adenocarcinoma." (PMID 24732908, 2014).
tumor (continued). "Although core fucosylation catalysed by fucosyltransferase 8 (FUT8) is known to regulate receptor signaling and tumor malignancy, its role in metabolic regulation of ccRCC remains poorly defined." (PMID 41857011, 2026). "Using the GEPIA2 database, we compared tumor tissues from TCGA with normal tissues from GTEx and found that SRD5A1, FUT8, and HES6 were significantly overexpressed in tumor tissues." (PMID 40729369, 2025). "Specifically, we observed that genes participating in the N-glycosylation pathway such as MAN1A1, MGAT1, FUT8, and B4GALT3 were significantly upregulated in neoplasia when compared with healthy subjects." (PMID 40087977, 2025). "Then, we performed expression difference analysis based on 1041 Tumor samples and 108 Normal samples from TCGA-LUADLUSC data, and the results suggested that FUT8 showed high expression in LUAD LUSC, p < 0.001." (PMID 40373023, 2025). "The FUT8 gene, identified via SMR analysis, was found to be overexpressed in tumor tissues and correlated with cellular functions and immune checkpoint genes, highlighting its potential as a therapeutic target." (PMID 40729369, 2025). "Previous studies have shown high expression of fut3 and fut8 in tumor-sphere and ESCC tumor tissues compared to matched healthy controls." (PMID 38911244, 2024). "Several glycosyltransferases, including MGAT5, FUT8, ST6GAL1, ST6GALNAC1 and ST8SIA1 have an established reputation as tumor-promoting enzymes." (PMID 35565254, 2022). "FUT8 modifies the activities of both the hepatocyte growth factor receptor and EGFR and affects tumor growth and invasion." (PMID 35752750, 2022). "FUT8 knockdown results in lessened TGFβ-inducing EMT, while an upregulation of FUT8 is observed during EMT—suggesting a positive feedback loop between FUT8 expression and TGFβ receptor signalling to promote EMT and tumour development." (PMID 33466384, 2021). "In the glycolysis pathway, PLOD1/2, FUT8 and TSTA3 are deregulated genes that participate in metabolism and glycolytic processes, which can influence the malignant transformation of cells, tumour development and metastasis." (PMID 32218455, 2020). "Additionally, older patients with a tumor exhibited elevated FUT2, FUT3, and FUT8 coexpression with tumor-promoting IL6ST, IL22RA1, TGFB1, and TGFBR1 genes compared with young tumor." (PMID 38456503, 2024). "In this study, we identified a novel m6A‐modified circFUT8, derived from exon 3 of FUT8, which was elevated in tumor tissues compared with adjacent noncancerous tissues." (PMID 37669906, 2023). "The significance of FUT8 expression changes in human tumours is still not fully elucidated, even though the existing studies have proved that the upregulation of FUT8 is prevalent in most human tumors." (PMID 34093814, 2021). "Moreover, significant up regulation of FUT8 (P = 0.054) and 1.85 fold up regulation of FUT5 mRNA levels were observed in tumor with advanced stage as compared to tumor with early stage." (PMID 34703796, 2021). "Compared to Fut8+/+ mice, Fut8-/- mice show limited liver carcinogenesis and liver regeneration, indicating the essential role of glycosylation on HGF-c-Met signaling and tumor progression." (PMID 32626713, 2020). "The Fut8 mRNA expression was significantly increased in tumorous tissues in these patients than that in non-tumor tissue controls." (PMID 24927126, 2014). "A significant increase in Fut8 expression, with a fold change about 1.82, was observed in tumor tissues with respect to non-tumor liver tissues (P = 0.01)." (PMID 24927126, 2014). "Thus, selective inhibition of the glycosylation enzymes that are responsible for core fucosylation, e.g., α1,6-fucosyltransferase (FUT8), will likely attenuate increased core fucosylation that was found on these glycoproteins in HCC tumor and serves as a potential therapeutic strategy for HCC." (PMID 35798744, 2022).
tumor (continued). "To assess whether overexpression of FUT8 enzyme in these cells were also impacting the overall fucosylation status of the tumor tissues, we stained these tumor sections for both the castrated and noncastrated xenograft tumors using LCA lectin." (PMID 32085441, 2020). "In addition, we compared Fut8 gene expression between paired tumor and non-tumor tissues from 24 patients with HBV-related HCC." (PMID 24927126, 2014). "Moreover, silencing Fut8 could inhibit tumor growth and metastasis without affecting the proliferation of normal lung epithelial cells, indicating the association of high Fut8 expression with deterioration and poor survival." (PMID 30619732, 2018). "Our data demonstrated that tumor tissues contained significantly lower mRNA levels of FUT3 (2.3 fold), FUT4 (2.7 fold), FUT5 (5.9 fold), FUT6 (3.0 fold), FUT8 (2.0 fold), and FUCA1 (2.6 fold) as compared to adjacent normal tissues." (PMID 34703796, 2021). "To determine the levels of Fut8 in tumor, we analyzed the expression of Fut8 in 24 pairs of HCC tumor tissues and their corresponding adjacent non-tumor liver tissue." (PMID 24927126, 2014).
infection (8 papers, 2011 to 2024). The state of being infected such as from the introduction of a foreign agent such as serum, vaccine, antigenic substance or organism. "In addition, highly expressed FUT8 can increase the susceptibility of cells to viruses and maintain a long-term state of infection." (PMID 37196106, 2023). "FUT8 plays an important role in the infection process of Escherichia coli, and its low expression helps to enhance the resistance of piglets to Escherichia coli." (PMID 39518877, 2024). "We used Fut8 tissue-specific knockdown in HCV-infected ICR4R+ transgenic mouse model or the FUT8 inhibitor 2FF in VSV-infected C57BL/6J mouse infection model in the following experiments." (PMID 38253527, 2024). "Among these genes, the mRNA level of FUT8 was significantly upregulated 3- and 10-fold at 6 and 12 h post-infection of HCV, respectively." (PMID 38253527, 2024). "After infection, the core fucosylation of the part 1 of small intestine and colon of Fut8+/+ mice showed an up-regulated pattern, significantly up-regulated in (part 1 of small intestine, p = 0.0047), but without statistic significance in colon (p = 0.1357)." (PMID 32528455, 2020). "To assess the interaction between IECs core fucosylation and gut microbiota, we investigated the gut microbiota of Fut8+/+ and Fut8+/– mice before and after infection." (PMID 32528455, 2020). "Next, we assessed the expression of core fucosylation and Wnt signaling pathway of Fut8+/+ and Fut8+/– mice before and after infection in the part 1 and part 4 of small intestine and colon by immunofluorescence and western blot." (PMID 32528455, 2020). "In agreement with those previous findings, we show here that U2OS cells bearing low levels of FUT8 protein exhibit a decreased infection ratio, potentially due to inefficient TGF-beta pathway signaling." (PMID 21625474, 2011). "Core fucosylation catalyzed by fucosyltransferase 8 (Fut8) is the major fucosylation pattern on the N-glycans of the surface glycoproteins on IECs, however, the role of IECs core fucosylation during infection remains unclear." (PMID 32528455, 2020). "Also, we detected more colonization of S. Typhi in Fut8+/– mice post infection when compared with Fut8+/+ + S. Typhi (p = 0.0417)." (PMID 32528455, 2020). "(b) due to the insufficiency and sophistication of the infection mouse models for other viruses, we only demonstrated that FUT8 promoted RNA viral replication (HCV and VSV) in both cellular and mouse infection models." (PMID 38253527, 2024). "Here, we found that the FUT8 inhibitor, 2FF, suppressed RNA viral replication (including HCV and VSV) in both cell culture and mouse infection models." (PMID 38253527, 2024). "Interestingly, post infection, the abundance of Firmicutes was found decreased in Fut8+/+ (66.37% vs. 54.28% before and post infection) and Fut8+/– mice (70.68% vs. 53.78%), in contrast to the elevation of Bacteroides abundance in Fut8+/+ (24.37% vs. 36.75%) and Fut8+/– mice (23.23% vs. 34.38%)." (PMID 32528455, 2020). "Western blot analysis showed that the levels of PI3 kinase p110 (the catalytic subunit of PI3K), phosphorylated Akt (pAKT), and NF-κB p-P65 were increased by infection with HCV, which was then reversed by treatment with FUT8 siRNA." (PMID 31022917, 2019). "Our data showed that core fucosylation and β-catenin were both up-regulated post infection of S. Typhi no matter in Fut8+/+ mice or in Fut8+/– mice." (PMID 32528455, 2020). "The results showed that compared with the control group, the expression level of FUT8 in IPEC-J2 cells infected with E. coli F18ac was significantly increased (p < 0.05), and the expression level of the FUT8 gene had no significant change after infection with E. coli F18ab (p > 0.05)." (PMID 36499043, 2022).
cardiovascular diseases (1 paper, 2023). "Researcher have confirmed that Fut8 could alter some functional properties through the induction of fucosylation, which is also a characteristic of cardiovascular diseases." (PMID 36670464, 2023).
intestinal disorder (1 paper, 2024). A non-neoplastic or neoplastic disorder that affects the small or large intestine. "Finally, a recent study reported a novel inhibitor of Fut8 that could inhibit the malignance of CRC cells; therefore, we could assume that novel agonists of Fut2 may also be developed for Fut2-deficiency-induced intestinal disorders." (PMID 38550777, 2024).
metabolic congenital disorder (1 paper, 2023). "Bi-allelic mutations in the FUT8 gene, resulting in defective FUT8 α1,6 fucosyltransferase activity and the absence of the core-fucosylated N-glycans, lead to the development of the severe metabolic congenital disorder of glycosylation with defective fucosylation 1 (FUT8-CDG) in humans." (PMID 36982780, 2023).
metabolic disorder (1 paper, 2023). "In humans, a rare inherited metabolic disorder called FUT8-CDG has been described, individuals affected have symptoms that are in part similar to those found in Fut8 knock-out mice and are caused by mutations in FUT8." (PMID 37598360, 2023).
renal disease (1 paper, 2022). "Second, serum FUT8 activity and FUT8 protein in other renal disease need to further confirmed." (PMID 36039648, 2022).
FUT8 also shares sentences with these, for which no sentence is quoted: papillary thyroid carcinoma (4 papers); head and neck squamous cell carcinoma (3); pancreatic cancer (3); papillary carcinoma (3); diffuse large B-cell lymphoma (2); gastric tumor (2); inflammatory bowel disease (2); lung diseases (2); metastatic colorectal cancer (2); psoriasis (2); thyroid tumours (2); adenocarcinoma (1); B cell lymphoma (1); bladder cancer (1); carcinoid tumor (1); chronic hepatitis (1); Cirrhosis (1); clear cell renal cell carcinoma (1); conduct disorder (1); congenital disorder of glycosylation (1); Crohn disease (1); Duchenne Muscular Dystrophies (1); ependymoma (1); galactosaemia (1); hematopoietic cancer (1); Hypertension (1); liver disease (1); malignant meningiomas (1); multiple sclerosis (1); nonalcoholic fatty liver disease (1).
A further 12 diseases each share a sentence with FUT8 in 1 paper.